NAGLU (N-acetyl-alpha-glucosaminidase)
Description:
Involved in the degradation of heparan sulfate.
Synonyms: NAG; CMT2V; MPS-IIIB; MPS3B; UFHSD
Tractability: Antibody: UniProt predicts a signal peptide or a membrane-spanning region. PROTAC: ubiquitination databases record sites on it; its protein half-life has been measured.
Target class: Enzyme; Hydrolase
Gene: Protein-coding gene on chromosome 17 (42,536,241 to 42,544,449, forward strand). Ensembl gene ENSG00000108784.
Subcellular location: Lysosome
Pathways (Reactome):
Disease: MPS IIIB - Sanfilippo syndrome B
Metabolism: HS-GAG degradation
Gene Ontology:
Molecular function: alpha-N-acetylglucosaminidase activity; iron ion sequestering activity
Biological process: heparan sulfate proteoglycan catabolic process; heparin proteoglycan metabolic process; nervous system development; carbohydrate derivative metabolic process; system development
Cellular component: extracellular exosome; lysosomal lumen; lysosome; vacuole
Genetic constraint (gnomAD): Loss-of-function variants: 33 observed, 42.89 expected, observed/expected ratio (o/e) 0.77, 90% interval 0.58 to 1.03. The upper end of that interval is the gene's LOEUF score, 1.03, which puts it in group 4 of 6, group 1 being the genes least tolerant of losing a copy. Missense variants: 892 observed, 899.92 expected, observed/expected ratio (o/e) 0.99, 90% interval 0.94 to 1.05. Synonymous variants: 415 observed, 386.97 expected, observed/expected ratio (o/e) 1.07, 90% interval 0.99 to 1.16.
Gene-disease validity (ClinGen):
ClinGen rates the evidence that NAGLU causes each of these diseases.
mucopolysaccharidosis type 3B (autosomal recessive): Definitive. A rare autosomal recessive lysosomal storage disease caused by deficiency of the enzyme N-acetyl-alpha-D-glucosaminidase.
Homologues: Orthologues: chimpanzee NAGLU (99% identical), macaque NAGLU (97% identical), pig NAGLU (87% identical), rabbit NAGLU (87% identical), dog NAGLU (85% identical), mouse Naglu (82% identical), rat Naglu (81% identical), guinea pig NAGLU (77% identical), tropical clawed frog naglu (57% identical), zebrafish naglu (57% identical), Drosophila melanogaster Naglu (41% identical), Caenorhabditis elegans K09E4.4 (31% identical).